IGFBP3 (insulin like growth factor binding protein 3)
Diseases named in the same sentence as IGFBP3 in open-access papers (continued):
Sharing a sentence is not in itself a finding about the gene and the disease.
lung carcinoma (continued). "The biological role and timing of IGFBP3 methylation in CRC is poorly understood; however, recent in vitro studies have reported that methylation-induced silencing of IGFBP3 may lead to significant resistance to cisplatin treatment in lung cancer." (PMID 25127039, 2014). "However, no significant decrease in risk of lung cancer was found for green tea drinkers with IGF2 and IGFBP3 genotypes (data not shown)." (PMID 22347413, 2012). "While the expression of IGFBP-3 may not be completely absent, a decrease in its expression can cause an elevation in the local availability of IGF-1 in lung tissue, thereby increasing the risk of developing lung cancer." (PMID 38540176, 2024). "It indicated that neither the circulating level of IGF-1 nor that of IGFBP-3 could act as long-term(the follow-up period were all more than five years and some even more than twenty years in the prospective studies we included in this meta-analysis)predictor of lung cancer." (PMID 23185474, 2012). "Using the CD44‐negative normal human lung cells (HFL1) and human lung cancer cells (A549) known to express CD44, we found that the IGFBP‐3 l‐peptide, but not its mutant, reduces A549 cell viability by disrupting HA‐CD44 interactions, a result consistent with our previous reports." (PMID 32592613, 2020).
Insulin resistance (61 papers, 2007 to 2025). Increased resistance towards insulin, that is, diminished effectiveness of insulin in reducing blood glucose levels. "Experimental studies further show that IGFBP-3 overexpression induces insulin resistance and dyslipidemia, while partial IGF-1 deficiency enhances gluconeogenic and lipogenic gene expression changes reversible with IGF-1 replacement." (PMID 41393761, 2025). "Due to IGF-1-independent action, IGFBP-3 has been associated with impaired glucose tolerance and insulin resistance in mouse models and in vitro studies as well." (PMID 41226444, 2025). "This study suggests that T2DM patients with low education level, history of insulin application, high insulin resistance, low serum IGFBP-3, and low creatinine values are more susceptible to MCI." (PMID 38698772, 2024). "Given the link between NAFLD and insulin resistance, the possible association between the rs2854744 (−202 G>T) promoter polymorphism of insulin-like growth factor binding protein 3 (IGFBP3) gene and NAFLD was investigated in this study." (PMID 37948568, 2023). "This aligns with other recently published data showing how low levels of IGFBP-3 increased the risk of cardiovascular disease and mortality and how low IGF-I/IGFBP-3 ratios increased the risk of metabolic syndrome and insulin resistance." (PMID 35528832, 2022). "IGFBP-3 is highly expressed by hyperinsulinemia in obese subjects, and its infusion reduces glucose utilization and glycogen synthesis, which suggests an association between insulin resistance and high levels of IGFBP-3." (PMID 29783731, 2018). "In another clinical study, IGF-1 combined with IGFBP-3 has been shown to improve insulin sensitivity and to reduce complications associated with insulin resistance in HIV/AIDS patients on antiretroviral therapy." (PMID 29422987, 2017). "IGF-I/IR traits that have been associated with CRC risk include IGF-I, IGFBP3, insulin, glucose, and homeostatic model assessment–insulin resistance [HOMA-IR] levels in this study." (PMID 29023587, 2017). "Based on these findings, we further investigated the effect of IGFBP-3 and its underlying mechanism in cytokine-induced insulin resistance in adipocytes and early manifestations of atherosclerosis in HAECs." (PMID 23383064, 2013). "Conversely, IGFBP-3 might represent a factor associated with a higher risk of insulin resistance and Type 2 Diabetes." (PMID 39578883, 2024). "Furthermore, Fgf15 expression is thought to be inversely associated with development of insulin resistance, whereas a positive correlation is reported for expression of insulin-like growth factor binding protein 3 (Igfbp3)." (PMID 18457598, 2008). "There is also evidence to suggest that insulin increases hepatic IGF-1 and IGFBP-3 production through direct regulation of the GH receptor, and thus, in patients with severe insulin resistance, IGF-1 deficiency may be due to both impaired hepatic production and accelerated IGF-I excretion." (PMID 36331627, 2023). "This is explained by the fluctuating levels of gonadotropins (FSH and LH) and testosterone, transient insulin resistance, and the concurrent rise in IGF-binding protein 3 (IGFBP-3) and the acid-labile subunit (ALS)." (PMID 40564774, 2025). "Transgenic mice with overexpression of IGFBP3 exhibited mild insulin resistance, accompanied by elevated levels of plasma leptin, glucose, and insulin." (PMID 40271123, 2025). "Modulation of this pathway can be monitored through measurement of fasting serum insulin, IGF-1, and IGFBP-3 levels, as well as by evaluating insulin resistance indices, such as the homeostatic model assessment for insulin resistance (HOMA-IR)." (PMID 41008741, 2025). "IGFBP3 interacts with cellular proteins involved in glucose metabolism regulation, consequently inducing insulin resistance and diminishing glucose uptake in adipose tissue." (PMID 38962743, 2024).
Insulin resistance (continued). "This reduction in TUDCA and CARN diminishes the inhibitory effect on IGFBP-3, thereby promoting subsequent insulin resistance." (PMID 39206042, 2024). "Senescent cells can directly cause insulin resistance and aggravate the burden of diabetes through SASP containing MCP-1, insulin-like growth factor binding protein 3 (IGFBP-3), high mobility group box 1 (HMGB-1), IL-6, and PAI-1." (PMID 37511296, 2023). "Data from several studies have concluded IGFBP-3 is elevated in obesity and has a role in insulin resistance, glucose intolerance, and less glucose clearance." (PMID 37629569, 2023). "Serum IGF-I and total IGFBP-3 levels, fasting plasma glucose levels, lipid profiles, insulin levels, C-peptide levels, homeostasis model assessment of insulin resistance (HOMA-IR) index, and glycated hemoglobin (HbA1c) levels were measured." (PMID 34239560, 2021). "IGFBP3 was shown to trigger insulin resistance independently of IGF binding, supported by decreased GLUT4 translocation to the plasma membrane as well as reduced Akt phosphorylation in response to insulin." (PMID 34690759, 2021). "On the other hand, due to an increase of the IGF-1/IGFBP-3 ratio, this stimulates the predominance of high mTOR-dependent metabolic activity and insulin resistance." (PMID 33333870, 2020). "OSM treatment regulates the expression of many proinflammatory adipokines causing insulin resistance (Timp1, PAI-1, Igfbp3, and Spp1) in adipose tissue." (PMID 31576964, 2020). "The patient had a low circulating IGF-1 concentration, extremely low IGFBP-3 concentration, insulin resistance and osteopenia." (PMID 30717585, 2019). "Taken together, these studies support a role for IGFBP-3 in obesity and the pathogenesis of insulin resistance." (PMID 30392760, 2019). "Especially, HFD feeding caused a ~4-fold increase in the protein levels of IGFBP-3 and MCP-1 that was associated with glucose utilization and insulin resistance in adipose tissues." (PMID 29783731, 2018). "In murine models, IGFBP-3 inhibits insulin-stimulated glucose uptake, while over-expression of IGFBP-3 in male transgenic mice results in fasting hyperglycaemia, impaired glucose tolerance, and insulin resistance." (PMID 26906713, 2016). "Exercise resulted in significant improvements on IGF-I, IGF-II, IGFBP-I, IGFBP-3, Insulin and Insulin resistance (P < 0.05)." (PMID 27562357, 2016). "In order to determine the effect of IGFBP-3 on TNF-α-induced insulin resistance, adipocytes were infected with IGFBP-3 alone and in the presence of TNF-α and insulin." (PMID 23383064, 2013). "Adiponectin is a hormone related to insulin sensitivity, and inhibition of its expression with IGFBP-3 may further exacerbate insulin resistance." (PMID 40538800, 2025). "In addition, Elks CM and colleagues also observed that treatment with oncostatin M induced gene expression of Timp1, Igfbp3, and Spp1 while alleviating insulin resistance." (PMID 38397957, 2024). "Although the role of IGFBP-3 in glucose and lipid metabolism is still not fully understood, it has been suggested that IGFBP-3 may inhibit adipocyte differentiation and may play an important role in the development of insulin resistance." (PMID 37510722, 2023). "Finally, IGFBP1 is negatively associated with impaired glucose tolerance and obesity and serves as a marker of HIS, while IGFBP3 correlates directly with hepatic insulin resistance and diabetes incidence." (PMID 36959287, 2023). "In addition, overexpression of IGFBP3 led to decreased glucose tolerance, insulin resistance, and hyperglycemia." (PMID 34690759, 2021). "In obesity, Timp1 (tissue inhibitor of metalloproteinases 1), Spp1 (osteopontin/secreted phosphoprotein 1), PAI-1 (plasminogen activator inhibitor-1) and Igfbp3 (insulin-like growth factor-binding protein 3) significantly increase in adipose tissue and contribute to the insulin resistance." (PMID 31576964, 2020).
Insulin resistance (continued). "Collectively, available data suggest that IGFBP-3 unfavorably influences insulin resistance although may have a favorable effect on adiposity." (PMID 30392760, 2019). "Higher insulin resistance may result in a lower ratio of IGF-1/IGFBP-3 in HCV-related CLD patients with severe steatosis." (PMID 29342898, 2018). "MiR-16 has been reported to play a key role in regulation of insulin signaling through a reduction in TNFα and suppressor of cytokine signaling 3 (SOCS3) signaling and increase in insulin-like growth factor binding protein-3 (IGFBP-3) levels to inhibit insulin resistance." (PMID 29214180, 2017). "TNFα and IGFBP-3 may both be involved in insulin resistance, as we previously demonstrated that TNFα is key to activation of an insulin resistance phenotype in REC, noted by increased IRS-1Ser307 and IRTyr960, with increased apoptosis of REC." (PMID 25073020, 2014). "In conclusion, these new discoveries for the inhibitory role of IGFBP-3 in obesity-induced insulin resistance and in the events occurring in the early stages of atherosclerosis, set the stage for a potential therapeutic role of IGFBP-3 in various aspects of metabolic syndrome." (PMID 23383064, 2013). "A Cox regression model was applied to test for the associations between cancer mortality and fasting serum glucose, insulin, glycosylated hemoglobin (HbA1c), C-peptide, insulin like growth factor (IGF-1), IGF binding protein 3 (IGFBP3) and estimated insulin resistance." (PMID 23405181, 2013). "IGFBP-3 has been shown to be associated with CVD, obesity and insulin resistance." (PMID 23383064, 2013). "Its correlation with HOMA-insulin resistance suggests that proteolysis of IGFBP-3 may be involved in the pathogenesis of obesity-induced insulin resistance." (PMID 23383064, 2013). "However, another study in insulin resistance, reported a reduction in both intramyocellular lipids and intrahepatic fat in a patient treated with rhIGF-I/IGFBP-3 (together with a post-treatment normalization of % HbA1C value)." (PMID 23148873, 2012). "Based upon the molecular interaction between HN and IGFBP-3 and the emerging link between AD and insulin resistance, we hypothesized that HN, in addition to its neuroprotective roles, may serve as a centrally-acting regulator of glucose homeostasis." (PMID 19623253, 2009). "The increased IGFBP3 levels in young CreERT2 mice, along with its increased expression in liver and perigonadal adipose tissue, may suggest a potential involvement of this binding protein in inducing insulin resistance." (PMID 36353242, 2022). "IGFBP-3 is the most abundant IGFBP in circulation and high IGFBP-3 may be a risk factor for insulin resistance in the development of T2D irrespective of IGF-1 levels." (PMID 29351335, 2018). "Results from the current study and studies of insulin and insulin resistance suggest that pancreatic carcinogenesis may be influenced by circulating insulin levels, whereas plasma levels of IGF-I, IGF-II, and IGFBP-3 may have little effect on the long-term risk for this malignancy." (PMID 17533398, 2007). "Overexpression of miR-16 increased IGFBP3 levels by decreasing TNF-α and SOCS3 signaling, inhibited insulin resistance, and protected retinal endothelial cells from HG-treated apoptosis." (PMID 40166052, 2025). "IGFBP-3 is the primary carrier protein for IGF-1 and exerts deleterious effects on insulin resistance and adipose tissue function by promoting the production of pro-inflammatory cytokines in adipocytes." (PMID 41226444, 2025). "miR-15b was found to have a role in the inhibition of insulin resistance by decreased TNFα and SOCS3 signaling and increased IGFBP-3 levels, resulting in REC protection from hyperglycemia-induced apoptosis." (PMID 35586497, 2022). "It plays a major role in the inhibition of insulin resistance via reduced TNFα and SOCS3 signaling and increased IGFBP-3 levels, resulting in REC protection from hyperglycemia-induced apoptosis." (PMID 32351607, 2020).
Insulin resistance (continued). "miR-15b and miR-16 play a role in the inhibition of insulin resistance via reduced TNFα and SOCS3 signaling and increased IGFBP-3 levels, resulting in REC protection from hyperglycemia-induced apoptosis." (PMID 25888955, 2015). "Taken together, these results demonstrate that miR-15b and miR-16 play a role in the inhibition of insulin resistance via reduced TNFα and SOCS3 signaling and increased IGFBP-3 levels, resulting in REC protection from hyperglycemia-induced apoptosis." (PMID 25888955, 2015). "However, IGFBP-3 and Cr levels were notably lower, and HOMA-IR (Homeostatic Model Assessment of Insulin Resistance) was significantly higher in T2DM-MCI patients compared to T2DM-NCI subjects (p < 0.05)." (PMID 38698772, 2024). "While both high and low IGF‐1 level may be associated with glucose intolerance and insulin resistance (U‐shaped effect), there are positive correlation between IGFBP3 (IGF‐binding protein 3) and glucose intolerance/insulin resistance." (PMID 37143466, 2023). "Additionally, different studies have proposed potential DNA methylation biomarkers in relation to plasma insulin levels, insulin secretion and insulin resistance such as those located in PPARGC1A, HTR2A, LY86, TFAM, GIPR, ADIPOQ, and IGFBP3 genes." (PMID 31208038, 2019). "The lower ratio of IGF-1/IGFBP-3 was also observed in patients with NAFLD, suggesting that a decrease in circulating free IGF-1 levels may account for exacerbation of insulin resistance and advanced hepatic steatosis." (PMID 29342898, 2018). "Zn deficiency may contribute to higher serum ferritin levels and lower IGF-1/IGFBP-3 ratios, surrogate measures for circulating free IGF-1 levels, and thus substantially exacerbate the insulin resistance in such patients." (PMID 29342898, 2018). "Therefore, we provide a novel finding that miR-15b and miR-16 play a role in preventing insulin resistance in REC cultured in high glucose, via reduced activation of TNFα and SOCS3 pathways and increased IGFBP-3 levels." (PMID 25888955, 2015). "This suggests that IGF-1 could be both a pro-atherogenic and an anti-atherogenic factor indicating that IGFBP-3 levels and its regulation on IGF-1 may be a better indicator and marker of insulin resistance." (PMID 23383064, 2013). "IGFBP-3 further inhibits TNF-α, CRP and high glucose-induced NF-kβ activity in human aortic endothelial cells and subsequently suppresses monocyte adhesion; suggesting a therapeutic target for obesity-induced insulin resistance and for events occurring in the early stages of atherosclerosis." (PMID 30392760, 2019). "This suggests that in the absence of IGFBP-3, mice may have a greater propensity to develop insulin resistance." (PMID 27448965, 2016). "To validate this results, we assessed the modulation of ICAM1, NQO1, IGFBP3, and THBS1 by POPs because, in addition to their role in cell adhesion, xenobiotic metabolism, angiogenesis, and cancer, these genes were reported to be related to adiposity, insulin resistance, and inflammation." (PMID 22262711, 2012). "In fact, serum concentration of IGFBP‐1, unlike IGFBP‐3 which binds 75–90% of circulating IGF‐I, is heavily influenced by the metabolic (i.e., insulin resistance, and insulin and glucagon levels) and nutritional (fasting and refeeding) state of the individual." (PMID 26443692, 2016). "More recently, we showed that IGFBP-3, independent of IGF-1, induces insulin resistance both at the liver and periphery through the hypothalamus as well as by direct action." (PMID 19623253, 2009).